RAB9BP1 (RAB9B, member RAS oncogene family pseudogene 1)
Synonyms: RAB9P1
Gene: Processed pseudogene on chromosome 5 (105,099,473 to 105,100,098, forward strand). Ensembl gene ENSG00000232159.
Diseases named in the same sentence as RAB9BP1 in open-access papers:
RAB9BP1 is named in the same sentence as 4 diseases in open-access papers, as found by Europe PMC text mining. Sharing a sentence is not in itself a finding about the gene and the disease. The quoted sentences say what the papers report.
cancer (2 papers, 2021 to 2025). A tumor composed of atypical neoplastic, often pleomorphic cells that invade other tissues. "It was found that deletions in the RAB9BP1, LOC101928523, and MALRD1 genes were associated with non‐cancer patients who had a family history of cancer (FHC)." (PMID 40556338, 2025). "HHIPL2, XPO1, SALRNA1, ZBTB45, ANP32AP1, ACTR3BP5, LOC100129138, GPR45, and CAB39L gene deletions were associated with non-cancer subjects without FCH (p < 0.05), while RAB9BP1, LOC101928523, and MALRD1 gene deletions were related to non-cancer patients with FCH (p < 0.05)." (PMID 33431054, 2021).
RAB9BP1 also shares sentences with these, for which no sentence is quoted: breast carcinoma (1 paper); glioma (1); tumor (1).